CEP250 (centrosomal protein 250)
Description:
Plays an important role in centrosome cohesion during interphase. Recruits CCDC102B to the proximal ends of centrioles. Maintains centrosome cohesion by forming intercentriolar linkages. Accumulates at the proximal end of each centriole, forming supramolecular assemblies with viscous material properties that promote organelle cohesion. May be involved in ciliogenesis.
Synonyms: C-Nap1; CEP2; CNAP1; CRDHL2
Tractability: Small molecule: a structure with a bound ligand is known. PROTAC: ubiquitination databases record sites on it; its protein half-life has been measured.
Gene: Protein-coding gene on chromosome 20 (35,455,164 to 35,519,280, forward strand). Ensembl gene ENSG00000126001.
Subcellular location: Cytoplasm, perinuclear region; Cytoplasm, cytoskeleton, microtubule organizing center, centrosome, centriole; Cytoplasm, cytoskeleton, microtubule organizing center, centrosome; Cytoplasm, cytoskeleton, cilium basal body; Cell projection, cilium, photoreceptor outer segment; Photoreceptor inner segment
Subcellular location (Human Protein Atlas): Centrosome; Basal body
Pathways (Reactome):
Cell Cycle: AURKA Activation by TPX2; Loss of Nlp from mitotic centrosomes; Loss of proteins required for interphase microtubule organization from the centrosome; Recruitment of NuMA to mitotic centrosomes; Recruitment of mitotic centrosome proteins and complexes; Regulation of PLK1 Activity at G2/M Transition
Organelle biogenesis and maintenance: Anchoring of the basal body to the plasma membrane
Gene Ontology:
Molecular function: protein binding; protein domain specific binding
Biological process: centriole-centriole cohesion; cilium assembly; intracellular protein localization; mitotic cell cycle; non-motile cilium assembly; positive regulation of protein localization to centrosome; protein localization to centrosome; regulation of centriole-centriole cohesion; detection of light stimulus involved in visual perception
Cellular component: centriole; centrosome; ciliary basal body; extracellular exosome; protein-containing complex; cytosol; microtubule organizing center; photoreceptor inner segment; photoreceptor outer segment; perinuclear region of cytoplasm; spindle pole centrosome
Genetic constraint (gnomAD): Loss-of-function variants: 235 observed, 304.39 expected, observed/expected ratio (o/e) 0.77, 90% interval 0.69 to 0.86. The upper end of that interval is the gene's LOEUF score, 0.86, which puts it in group 3 of 6, group 1 being the genes least tolerant of losing a copy. Missense variants: 2,462 observed, 2,870 expected, observed/expected ratio (o/e) 0.86, 90% interval 0.83 to 0.89. Synonymous variants: 1,075 observed, 1,182.1 expected, observed/expected ratio (o/e) 0.91, 90% interval 0.86 to 0.96.
Gene-disease validity (ClinGen):
ClinGen rates the evidence that CEP250 causes each of these diseases.
cone-rod dystrophy and hearing loss 2 (autosomal recessive): Definitive.
Homologues: Orthologues: chimpanzee CEP250 (99% identical), macaque CEP250 (96% identical), pig CEP250 (85% identical), rabbit CEP250 (83% identical), dog CEP250 (82% identical), rat Cep250 (79% identical), mouse Cep250 (79% identical), zebrafish crocc2 (19% identical), zebrafish si:dkey-230p4.1 (19% identical), Drosophila melanogaster Root (16% identical), Caenorhabditis elegans lfi-1 (14% identical), zebrafish cep135 (9% identical). Paralogues in human: CROCC (23% identical), CROCC2 (17% identical), CEP135 (9% identical), TSGA10 (6% identical).
Diseases named in the same sentence as CEP250 in open-access papers:
CEP250 is named in the same sentence as 38 diseases in open-access papers, as found by Europe PMC text mining. Sharing a sentence is not in itself a finding about the gene and the disease. The quoted sentences say what the papers report.
Usher syndrome (11 papers, 2016 to 2025). A syndromic diseae characterized by the association of sensorineural deafness (usually congenital) with retinitis pigmentosa and progressive vision loss. "The ages of the affected individuals in this study ranged from the late 30 s to the early 40s, which is older than that reported previously for atypical Usher syndrome caused by variants in CEP250." (PMID 37759551, 2023). "It is known that nonsense mutations in CEP250 cause atypical Usher syndrome, characterized by early onset sensorineural hearing loss and relatively mild retinitis pigmentosa (RP)." (PMID 37759551, 2023). "This postulation is consistent with the late-onset and relatively mild phenotype of atypical Usher syndrome or nonsyndromic RP of hearing loss caused by variants in CEP250." (PMID 37759551, 2023). "Concerning CEP250, previously associated to atypical Usher syndrome, the homozygous missense A609V is a seemingly mild amino acid substitution embedded in a long evolutionarily conserved stretch of the Smc domain." (PMID 28005958, 2016). "CEP250: A homozygous nonsense variant in CEP250 accompanied by a heterozygous or homozygous nonsense variant in PCARE was found to be related to an atypical Usher syndrome in a consanguineous family." (PMID 40149483, 2025). "Furthermore, we detected two novel nonsense mutations in CEP250 in a patient with a disease mimicking Usher syndrome that associates visual impairment due to cone-rod dystrophy and progressive hearing loss." (PMID 30459346, 2018). "Initially diagnosed with Usher syndrome, the WGS study revealed two variants, c.5383dup and c.5050del, in the CEP250 gene, associated with a syndromic form of RP known as cone-rod dystrophy and sensorineural hearing loss type 2." (PMID 38674450, 2024). "Cep250 is a candidate gene for atypical Usher syndrome, and this study describes the development of a Cep250 KO mouse model to investigate its pathogenesis." (PMID 37240188, 2023). "To date, there have been five reports on the association between CEP250 pathogenic variants and atypical Usher syndrome or nonsyndromic RP." (PMID 37759551, 2023). "PDZD7 may act as a modifier gene for USH, but HARS, ABHD12, CIB2, CEP250, CEP78, ESPN, and ARSG could be grouped in a separate syndromic “deaf–blindness” category, to avoid diagnostic pitfalls and misinformation during genetic counseling for Usher syndrome." (PMID 35353227, 2022). "Our patient with the CEP250 mutations presented with progressive hearing loss and mild macular affectation with lowering of the visual acuity and photophobia, which are similar symptoms to those of the latter work, thus consolidating its role as a gene responsible for mimicking Usher syndrome." (PMID 30459346, 2018). "It is not clear if CEP250 variants alone may or may not be sufficient to cause Usher syndrome." (PMID 40149483, 2025).
retinal degeneration (5 papers, 2020 to 2025). Degeneration of the retina. "Cep250 KO mice experience a late-stage retinal degeneration that manifests as the atypical USH phenotype." (PMID 37240188, 2023). "Defects in several of these ciliary DEGs have been associated with USH (Cep250 (atypical USH), Pcdh15 (USH1F) or other retinal ciliopathies Fam164a (RP28) leading to retinal degenerations as seen in USH2C patients with pathogenic variants in the ADGRV1 gene." (PMID 40103630, 2025). "The study of Cep250-knock-in mice harboring the same mutation showed that a lack of Cep250 leads to severe retinal degeneration." (PMID 35353227, 2022). "Herein, we identified a novel nonsense homozygous variant in CEP250 (c.3511C>T; p.Gln1171Ter) among the family members with progressive moderate sensorineural hearing loss in nonsyndromic autosomal recessive type but without retinal degeneration." (PMID 37759551, 2023).
cone-rod dystrophy (4 papers, 2018 to 2025). Inherited retinal dystrophies that belong to the group of pigmentary retinopathies. "However, WGS revealed two variants in the CEP250 gene, associated with retinitis pigmentosa, cone-rod dystrophy, and sensorineural hearing loss." (PMID 38674450, 2024). "Similarly, CEP250 is localized in cilia and its dysfunction has been associated with a moderate form of RP with progressive SNHL or with a cone-rod dystrophy combined with deafness." (PMID 39672920, 2025). "The novel variant CEP250 c.3511C>T; p.Gln1171Ter was associated with slowly progressive sensorineural hearing loss, but was not related to ocular phenotypes such as cone-rod dystrophy or RP." (PMID 37759551, 2023).
breast carcinoma (3 papers, 2014 to 2022). "The upstream sequence of exon 22 of CEP250 gene (ENST00000356095) was searched for in breast cancer cell line BT474, and was found to be a sequence from exon 16 to exon 19 of ZMYND8 gene (ENST00000360911)." (PMID 24533689, 2014). "In breast cancer cells, ZMYND8 is expressed as a fusion protein with centrosomal protein 250 (CEP250), a factor required for centriole–centriole cohesion during interphase of cell division." (PMID 36520265, 2022). "In breast cancer cells, ZMYND8 may be present as a fusion protein with centrosomal protein 250 (CEP250), which is required for centriole–centriole cohesion during interphase." (PMID 33670804, 2021).
hearing loss (3 papers, 2018 to 2023). "In conclusion, a nonsense variant in CEP250 results in a deficit of centrosome localization and hair cell degeneration in the cochlea, which is associated with the progression of hearing loss in humans and mice." (PMID 37759551, 2023). "Given that the onset of hearing loss occurs in adulthood, CEP250 in the cochlea may be involved in the maintenance of hair cell structure and function, but not in the developmental stage." (PMID 37759551, 2023). "In addition to CLIC5, only the CEP250 gene shows compound heterozygous synonymous variants that co-segregate with hearing impairment, which was unlikely to be the cause of the disease." (PMID 33114113, 2020).
COVID-19 (2 papers, 2020 to 2024). A disease caused by infection with severe acute respiratory syndrome coronavirus 2. "recently introduced CEP250 as candidate therapeutic targets in COVID-19, and revealed strong association between CEP250 and the SARS-CoV-2 nonstructural protein-13 (Nsp13)." (PMID 38742101, 2024). "Finally, since WDB002 targets CEP250, it may be a promising starting point for developing a treatment for COVID-19." (PMID 32606248, 2020).
Azoospermia (1 paper, 2025). Absence of any measurable level of sperm,whereby spermatozoa cannot be observed even after centrifugation of the semen pellet. "Mutations in centrosomal proteins such as Cep112, Cep250, Cntrob, and Odf1 result in defects in head-tail attachment and can lead to headless sperm and non-obstructive azoospermia that contributes to infertility." (PMID 40294089, 2025). "These centrosome components are critical for maintaining the head-tail attachment, as exemplified by the fact that mutation of centrosomal genes Cep112, Cep250, Cntrob, and Odf1, lead to acephalic spermatozoa (headless sperm) and non-obstructive azoospermia." (PMID 40294089, 2025).
colorectal cancer (1 paper, 2021). A primary or metastatic malignant neoplasm that affects the colon or rectum. "By association analysis, we were able to identify that the methylation levels of the CEP250, RAB21, and TNPO3 genes independently play crucial roles in colorectal cancer prognosis." (PMID 33670198, 2021).
inflammatory bowel disease (1 paper, 2021). A spectrum of small and large bowel inflammatory diseases of unknown etiology. "There is also a genome-wide association study that shows the association of CEP250 with inflammatory bowel disease." (PMID 33670198, 2021).
lymphoma (1 paper, 2011). A malignant (clonal) proliferation of B- lymphocytes or T- lymphocytes which involves the lymph nodes, bone marrow and/or extranodal sites. "CEP250 is a centrosomal protein and was the only antigen specifically recognised by sera from lymphoma patients." (PMID 21887344, 2011). "CEP250 expression was widely upregulated in lymphoma and myeloma cell lines, when compared to levels in normal fractionated control cells." (PMID 21887344, 2011). "However, this does not exclude the possibility that the five antigens preferentially recognised by sera from patients (TCEB3, BECN1, CEP250, c14orf93 and ZBTB44) may have a role in the pathobiology of lymphoma." (PMID 21887344, 2011).
male infertility (1 paper, 2021). The inability of the male to effect fertilization of an ovum after a specified period of unprotected intercourse. "The invalidation of Cep250 induces centrosome precocious separation at the early stages of spermatogenesis, resulting in male infertility." (PMID 35127699, 2021). "The Cep250-/- mice presented with no major defects, apart from male infertility due to a reduction in the spermatogonial pool and the meiotic blockade." (PMID 35127699, 2021).
medulloblastoma (1 paper, 2023). A malignant, invasive embryonal neoplasm arising from the cerebellum. "To further gain insight into the function of PHF5A in medulloblastoma, we first verified that downregulation of ABL1 reduced pY36-PHF5A level in centrosome, and pY36-PHF5A decreased the protein level of CEP250 in Daoy cells." (PMID 36759599, 2023).
pancreatic cancer (1 paper, 2023). "For prognostic prediction, we developed an immune-related prognostic risk model (IRPM) based on four immune-related prognostic genes in pancreatic cancer, RHOF, CEP250, TSC1, and KIF20B." (PMID 38203311, 2023).
progressive sensorineural hearing loss (1 paper, 2023). "In our study, patients with the CEP250 p.Gln1171Ter variant did not have any ocular phenotype, but only had auditory phenotypes, such as progressive sensorineural hearing loss (i.e., NSHL)." (PMID 37759551, 2023).
Retinal dystrophy (1 paper, 2019). Retinal dystrophy is an abnormality of the retina associated with a hereditary process. "There is some evidence that mutations in human CEP250 lead to retinal dystrophy and SNHL, and CEP250 is known to interact with proteins implicated in rhodopsin trafficking (NEK2 and NINL)." (PMID 30421101, 2019).
cancer (4 papers, 2020 to 2025). A tumor composed of atypical neoplastic, often pleomorphic cells that invade other tissues. "In addition, we identified that CHEK1 activated NEK2 (data not shown), an established MM CIN marker reported in our previous study, while NEK2 stimulated CIN in cancer cells by regulating CEP250, a core centrosomal protein essential for centriole–centriole cohesion." (PMID 34090465, 2021). "HER2-enriched cancers involved four regulators of PLK1 activity at G2/M transition in the cell cycle, CEP63, CEP250, NEDD1, and HAUS3." (PMID 40700427, 2025). "Studies have confirmed that NDC80 and CEP250, in connection with NEK2, participated in the mechanism of some cancers." (PMID 33109182, 2020). "At the single nucleotide polymorphism (SNP) mutation level and transcriptional level, we found that MAP4, YWHAG, KSR2, SPAG9, and CEP250 gene-related loci are different in cancer and paracancer tissues, and MAP4, YWHAG, CEP135, and CEP250 differed significantly at the transcriptional level." (PMID 36705386, 2023).
tumor (4 papers, 2017 to 2023). "In univariate Cox regression analysis, HCC recurrence, pathologic stage, tumor size, and NEK2, NDC80 and CEP250 mRNA expression were all significantly associated with HCC patients’ survival." (PMID 33109182, 2020). "In this study, 105 immune-related genes from tumor gene sets were identified as IRPGs in PAAD patients by the univariate Cox analysis, and 4 genes of IRPGs, RHOF, CEP250, TSC1, and KIF20B were then used to construct the IRPM." (PMID 38203311, 2023). "The NEK2, NDC80 and CEP250 mRNA expressions were different in relation to age, weight, recurrence status, histological grade, family HCC history, pathologic stage, tumor size, and survival time." (PMID 33109182, 2020). "Similarly, the normal lung tissues had a single nucleotide change in CEP250, C9orf66, and HIST1H1D, compared to those in the tumor samples, hg19, and dbSNP138." (PMID 29262625, 2017).
retinal disorder (2 papers, 2023). Any disease or disorder of the retina. "Two years later, a cohort of 33 pedigrees with various retinal disorders was analysed using the WES technique, identifying another mutant in CEP250 (Cep250 c.1826C > T p.A609V) that caused non-syndromic IRD and influenced cilia formation." (PMID 37240188, 2023).
CEP250 also shares sentences with these, for which no sentence is quoted: deaf (2 papers); Bardet-Biedl syndrome (1); Blindness (1); celiac disease (1); diabetes (1); genetic disorders (1); Hearing impairment (1); hepatocellular carcinoma (1); Infertility (1); liver cancer (1); lung carcinoma (1); myeloma (1); neurological disorders (1); Obesity (1); Photophobia (1); retinal ciliopathy (1); retinitis pigmentosa (1); sensorineural hearing loss (1); type 2 diabetes (1); Usher syndrome type 1G (1).